ENSG00000202183
Synonyms: LOC124900496
Gene: Small nucleolar RNA gene on chromosome X (82,561,201 to 82,561,347, forward strand). Ensembl gene ENSG00000202183.
Gene Ontology:
Biological process: RNA processing
Cellular component: nucleolus
Homologues: Orthologues: rat LOC120100360 (58% identical), rat LOC120099067 (57% identical), mouse Gm24728 (54% identical), rat LOC120095411 (54% identical), rat LOC120099453 (50% identical), mouse Gm54692 (48% identical), rat LOC120102009 (40% identical). Paralogues in human: SNORA4 (68% identical).